APOA1 (apolipoprotein A1)
Diseases named in the same sentence as APOA1 in open-access papers (continued):
Sharing a sentence is not in itself a finding about the gene and the disease.
cardiovascular disease (continued). "Three large cohort studies also exhibited a consistent outcome that both ApoB and ApoA1 had independent and equal predictive values, and ApoB/A1 ratio was the strongest and most specific indicator for cardiovascular disease that was superior to the cholesterol ratios." (PMID 31123322, 2019). "The relationship between HDL-C and cardiovascular diseases is primarily due to cholesterol efflux facilitated by apolipoprotein A1 during the process called the reverse cholesterol transport and HDL-C acceptors or by diffusion leads to HDL-C mobilization from cell membrane to hepatic storage." (PMID 29631590, 2018). "It is noteworthy, that lower ALB, aPOA1, TP and GGT levels, which may reflect increased proteinase activity, and higher AST/ALT ratios are always associated with both liver and cardiovascular disease." (PMID 28061459, 2017). "Of the metabolic and cardiovascular disease markers high triglyceride concentration (p = 0.02 in men and p = 0.001 in women) and high apolipoprotein B/apolipoprotein A1 ratio (p = 0.04 in men and p = 0.03 in women) were independently associated with low 25OHD level." (PMID 25000408, 2014). "Among these were protein biomarkers for different organ diseases such as deficiency of thyroid binding (thyroxine-binding globulin), chronic kidney dysfunctions (cystatin C), hypercoagulation disorders (plasminogen), and cardiovascular diseases (apolipoprotein A1, B)." (PMID 22538116, 2012). "Proper APOA1 configuration on the HDL surface is critical for binding and activation of critical modifying enzymes such as LCAT, directly linked to HDL deficiencies and development of cardiovascular disease, underscoring the importance of APOA1 structure as a key driver of HDL function." (PMID 41167396, 2025). "It is important to determine whether adding information on apolipoprotein B (apoB) and apolipoprotein A1 (apoA1), lipoprotein (a) or lipoprotein-associated phospholipase A2 to total cholesterol (TC), LDL-C and HDL-C improves cardiovascular disease (CVD) risk prediction." (PMID 24573394, 2014). "The ratio of two apolipoproteins with distinct functions, Apolipoprotein B/Apolipoprotein A1 (APOB/APOA1), has been proposed as a novel assessment index for the evaluation of cardiovascular diseases." (PMID 40787622, 2025). "APOA1 is the main protein component of high-density lipoprotein (HDL) in plasma and is commonly used as a biomarker to predict cardiovascular disease." (PMID 40739302, 2025). "Apolipoprotein A1 (APOA1), the primary protein constituent of high-density lipoprotein cholesterol (HDL-c), appears to establish a potential link between MAFLD and cardiovascular disease." (PMID 39764250, 2024). "This study aimed to study the relationship between auto-antibodies against apolipoprotein A1 (anti-apoA1 IgG), human immunodeficiency virus (HIV) infection, anti-retroviral therapy (ART), and the tryptophan pathways in HIV-related cardiovascular disease." (PMID 38414919, 2024). "Over the past decade, autoantibodies against apolipoprotein A-1 (anti-apoA-1 IgG), the principal protein component of high-density lipoprotein (HDL), have emerged as an independent biomarker for cardiovascular disease and mortality." (PMID 34888742, 2022). "Apolipoprotein A1 (APOA1), a component of high-density lipoprotein, exerts a favorable effect on the prevention of many cardiovascular diseases." (PMID 36046240, 2022). "APOA1 is a component of high-density lipoprotein (HDL) and therefore often used as marker for cardiovascular diseases." (PMID 34679037, 2021). "The lipid homeostasis system is covered by more than 20 factors, several of which—including apolipoprotein A1 (APOA1), apolipoprotein B (APOB), and apolipoprotein(a) (LPA)—are important predictors of cardiovascular diseases." (PMID 33444735, 2021).
cardiovascular disease (continued). "ApoA1 is the main protein component of high-density lipoprotein (HDL), which is involved in reverse cholesterol transport and is generally considered protective against cardiovascular disease." (PMID 39273041, 2024). "Several new markers have been introduced as alternative means to refine risk estimation beyond LDL-c in the presence of cardiovascular disease, such as non-HDL-c, TC/HDL-c ratio, and the apoB/apoA1 ratio." (PMID 38443803, 2024). "Finally, it would have been helpful if we had checked apolipoprotein A1 and B. Apolipoprotein A1 and B are the major protein components of HDL and LDL, respectively, and are well known biomarkers for prediction of cardiovascular diseases." (PMID 25889692, 2015). "Nevertheless, the disease phenotype associated APOA1 rs670 remains significant without HDL-C differences, as has been reported in a number of studies on metabolic/cardiovascular diseases." (PMID 23829168, 2013). "Also, comparing the amino acid related to HDL (ApoA-1), which is identical between humans, dogs, cats, and pigs, shows that the role of HDL in cardiovascular disease may be similar among species." (PMID 39590316, 2024). "Finally, forty years ago, clinicians were not using A2M, ApoA1 was interesting for predicting cardiovascular diseases, and haptoglobin was mostly used for the diagnosis of hemolysis." (PMID 35327501, 2022). "Moreover, it is hard to speculate on the role and possible involvement of apoA1 isoforms in cardiovascular diseases: to date neither the composition of these isoforms, nor the influence of other factors (age, treatment, smoking, etc.)on the level and composition of these isoforms is known." (PMID 21631938, 2011). "Several new markers have been introduced as alternative means to refine risk estimation beyond LDL-c from Friedewald’s formula in the presence of cardiovascular disease, such as non-HDL cholesterol, total cholesterol/HDL-c ratio, non-HDL cholesterol/HDL-c, and the apoB/apoA1 ratio." (PMID 31744496, 2019).
tumor (188 papers, 2010 to 2025). "The underlying mechanism responsible for the anti-tumorigenic role of APOA1 is that APOA1 can convert cancer-linked macrophages from being pro-tumor M2 to becoming the anti-tumor M1 phenotype." (PMID 38067270, 2023). "APOA1 changes the phenotypic expression of the macrophages from pro-tumor (M2) to anti-tumor (M1), and blocks tumor-associated angiogenesis by downregulating MMP-9 expression." (PMID 38067270, 2023). "A mouse model study showed that high levels of circulating APOA-1 were associated with an increased tumor burden." (PMID 38067270, 2023). "To analyze a potential antitumor effect of HDL particles in vivo, we first compared tumor growth kinetics of WT and APOA1-deficient mice (Apoa1 KO), which exhibit dramatically reduced plasma HDL levels." (PMID 35577388, 2022). "A reported study demonstrated that in the tumor microenvironment, ApoA1 worked as a potent immunomodulatory agent by transforming tumor-associated macrophages from a pro-tumor to an antitumor phenotype." (PMID 35100989, 2022). "For example, B16F10 melanoma-bearing mice expressing a human APOA1 transgene exhibited reduced tumor burden, decreased tumor-associated angiogenesis, lower metastatic potential, and enhanced survival." (PMID 35577388, 2022). "As APOA1 (mimetic peptides)/HDL has been previously demonstrated to affect tumor angiogenesis and tumor-associated immune-cell populations, we measured intratumoral hypoxia and immune cell infiltration." (PMID 35577388, 2022). "Lower urinary APOA-1 protein levels showed a significant association with HG tumours (<20 ng; 84.6% versus 15.4%), while LG tumours were associated with six times higher expression (≥20 ng)." (PMID 35955727, 2022). "APOA1 was shown to inhibit tumor development, and low serum levels of APOA1 are associated with poor prognosis." (PMID 35421932, 2022). "Third, ApoA-1, a potential immunomodulator, converts the tumor-associated macrophage phenotype from a tumor-promoting phenotype (M2 type) to an anti-tumor phenotype (M1 type)." (PMID 32391278, 2020). "BTG4 and RERG genes implicated in tumor growth repression were found to be the most strongly up-regulated genes by anti-apoA-1 IgGs." (PMID 33245719, 2020). "Our results demonstrate that age, T stage, tumor location, CEA level, number of monocytes, LMR and ApoA1 are associated with immune cell densities in the tumor microenvironment." (PMID 31300050, 2019). "As the main structural protein of HDL, APOA1 has anti-atherosclerotic, anti-inflammatory, antioxidant, and anti-endotoxic effects, and chronic inflammation, oxidative stress, lipids, and cholesterol are associated with tumor development." (PMID 35421932, 2022). "Therefore, we expressed murine APOA1 in the liver of Panc02 tumor-bearing mice using adeno-associated viral particles (AAV-APOA1)." (PMID 35577388, 2022). "The inverse association between APOA1 expression and PD-L1 implies that APOA1 plays a tumor suppressor role in KIRC and may be a novel therapeutic target for KIRC." (PMID 35858961, 2022). "Moreover, ApoA1 was found to have an effective immunomodulatory role in the tumor microenvironment, for it can change tumor‐associated macrophages from pre‐tumor M2 to anti‐tumor M1 phenotype." (PMID 33336932, 2021). "This tumor-specific population was expanded in mice treated with a vector encoding IFNα or ApoA1-IFNα, indicating that both vectors could enhance T cell-mediated antitumor effector immune responses." (PMID 28029653, 2017). "In the current study, extensive tumor necrosis was associated with a high APOB/APOA1 ratio, which could, at least partly, be related to the association between tumor necrosis and systemic inflammation." (PMID 28710487, 2017). "The present study is the first to show that preoperative serum ApoA-1 levels retain their prognostic value in those subgroups at risk for which conventional clinicopathological variables offer limited information predicting tumor recurrence." (PMID 27683106, 2016).
tumor (continued). "The trend of APOA1 expression may be different in the pre-diagnostic stages of CRC as compared to post-diagnostic stages which generally included advanced tumour stages." (PMID 26463353, 2016). "In conclusion, ApoA1 affects tumor growth and its deficiency may favor tumor progression." (PMID 35100989, 2022). "Another example of biomimetic engineering involves apoA1-bExo, an exosome functionalized with the tumor-targeting apolipoprotein A1 (apoA1), used to deliver siRNA targeting neutral sphingomyelinase 2 (nSMase2), an enzyme implicated in exosomal PD-L1 secretion." (PMID 40943628, 2025). "In oncology, APOA1 has been shown to regulate tumor proliferation, modulate the immune microenvironment and correlate with the prognosis, suggesting potential parallel functions in placental pathophysiology." (PMID 40778280, 2025). "In vivo studies have demonstrated the potent anti-tumorigenic effects of ApoA1, including significant suppression of tumor growth and metastasis in mouse tumor models." (PMID 40821786, 2025). "Our findings demonstrate that UTUC secreted tumor-derived factors, with apolipoprotein A1 (Apo-A1) being the predominant factor, which upregulated arginase-1 expression in neutrophils." (PMID 40358184, 2025). "Both in vitro and in vivo studies have demonstrated that APOA1 can inhibit tumor initiation and progression." (PMID 39399493, 2024). "Since there were too many missing data on cytogenetic or molecular biological information in our cohort, we were unable to reveal the correlation between serum ApoA1 levels and the biological tumor characteristics of patients with DLBCL." (PMID 38212711, 2024). "Among the dominant factors secreted by UTUC tumor tissue, apolipoprotein A1 (Apo-A1) exhibited a positive correlation with NLR." (PMID 38534755, 2024). "Previous studies demonstrated that ApoA1 has been shown to be involved in chemoresistance and metastasis in some types of solid tumors, and ApoA1 mimetic peptides had been confirmed to have anti-tumor effects." (PMID 38212711, 2024). "An ApoA1-modified tumor-derived exosome coupled with siRNA targeting neutral sphingomyelinase type 2 also effectively targeted tumor cells and enhanced the antitumor activity of CD8+ T cells by reducing the level of PD-L1." (PMID 39204373, 2024). "WB analysis of serum and tumor tissue specimens confirmed the upregulation of eight proteins: APOA1, HBB, CAH1, HBD, LPA, SAA4, PF4V1, and APOE." (PMID 39194522, 2024). "On the other hand, ApoA1, vitronectin, and IgG found in coronas of all samples were shown to facilitate liposome interactions with tumor cells." (PMID 37376203, 2023). "Pseudotime analysis suggested the APOA1+ HCC subpopulation to be the origin of tumor development, which again demonstrates the potential of APOA1 as a marker for early HCC detection." (PMID 37333982, 2023). "Apolipoprotein A1 (APOA1) is a major apoprotein constituent of high-density lipoproteins that plays important roles in tumor invasion and metastasis." (PMID 38003549, 2023). "An ApoA1-armed oncolytic adenovirus is also developed, which restores antitumor immunity and elicits long-term tumor-specific immune surveillance." (PMID 37474548, 2023). "In other words, the DOX concentration in the tumor tissues of 4T1 tumor-bearing mice treated with ApoA1-LipDOX was three times higher than the concentration of free DOX in the same region." (PMID 37375753, 2023). "HDL-C, a potential tumor inhibitor, plays anti-inflammatory and antioxidant roles mainly through apolipoprotein A1(ApoA1) and paraoxonase 1(PON1)." (PMID 36811728, 2023). "Together, these data demonstrate that an oncolytic adenovirus engineered to express APOA1 achieves superior tumor clearance with a laudable safety profile." (PMID 37474548, 2023). "Recent findings have revealed the crucial roles of APOA1 in inflammation, tumor growth, angiogenesis, invasion, and metastasis." (PMID 38003549, 2023).
tumor (continued). "These alterations were found to reduce the tumor burden in the lung, suggesting the use of oral APOA1 mimetic peptides as therapeutic agents in the intestine–lung axis." (PMID 38067270, 2023). "Post-gastrectomy, their APOA levels dramatically decreased; hence, it is believed that APOA-1 is secreted by the tumor cells." (PMID 38067270, 2023). "A recent study found that APOA1 had an inverse relationship with tumor size in male PTC patients, especially in the younger age group after adjusting for age." (PMID 38067270, 2023). "On the other hand, research has been carried out to study the mechanism of action of the APOA1 mimetic peptide D-4F in inhibiting tumor progression." (PMID 38067270, 2023). "Since its expression increases with disease progression, it is suggested that the source of APOA1 is the tumor cells." (PMID 38067270, 2023). "To avoid impairing neuronal cholesterol homeostasis, we employed an alternative strategy that targeted TAM cholesterol efflux via ApoA1 to control tumor immunity." (PMID 37474548, 2023). "We found that HIF, a TF that induces hypoxic gene expression and helps tumor cells adapt to hypoxic environments, was highly expressed in the APOA1+ HCC subpopulation." (PMID 37333982, 2023). "Tumor control was associated with a reduced cholesterol levels in the TME, as evidenced by lower cholesterol levels in TIFs of mice bearing APOA1-expressing GBMs compared to those bearing puromycin-expressing GBMs." (PMID 37474548, 2023). "Studies have shown that a preoperative decrease in ApoA1 level is related to aggressive tumor features and shortened disease-free survival in solid tumors." (PMID 36811728, 2023). "Having shown that ApoA1 reduced the immunosuppression of TAM on tumor-specific OT-1 cells, we next sought to delineate how ApoA1 manipulates the TAM-T-cell axis for GBM tumor control." (PMID 37474548, 2023). "AdVAPOA1 selectively infected tumor cells, produced viral progeny, and secreted ApoA1 protein in orthotopic GBM tumors." (PMID 37474548, 2023). "By contrast, ApoA1 functions as a tumor suppressor involved in lipid metabolism reprogramming in PC." (PMID 36506554, 2022). "Thereby, rHDL reduced Panc02 tumor weight significantly compared with Apoa1 KO mice, pointing toward a moderate antitumor effect of rHDL particles also in vivo." (PMID 35577388, 2022). "The levels of APOA1, APOH, HEP2, GELS, PZP and PEDF were associated with neoadjuvant pathological tumor (ypT) stage." (PMID 35945555, 2022). "In contrast, the APOA1 mimetic peptide D-4F significantly increased tumor latency and reduced tumor outgrowth." (PMID 35577388, 2022). "Robust expression levels of the APOA1 mRNA were detected in the livers of end stage Panc02 tumor-bearing WT and Apoa1 KO AAV-APOA1 mice, whereas APOA1 mRNA levels were absent from livers of Apoa1 KO mice." (PMID 35577388, 2022). "This is supported by functional studies showing that APOA1 plays a vital role in tumour growth, angiogenesis, invasion, and metastasis." (PMID 35955727, 2022). "By combining in vitro analyses that elucidate the impact of HDL particles on tumor cells with in vivo experiments using Apoa1 KO mice, we show that the HDL particle composition likely determines its antitumor activity." (PMID 35577388, 2022). "Several studies have found that APOA1 plays important roles in tumor growth, angiogenesis, and invasion, and metastasis." (PMID 35421932, 2022). "In vivo experimental results showed that ApoA1 was transformed from pro-tumor M2 macrophages to anti-tumor M1 phenotypes, and tumors were infiltrated by cytotoxic cells." (PMID 35100989, 2022). "In the case of EOC, in a mouse model of ovarian epithelial papillary serous adenocarcinoma, the overexpression of human APOA1 not only elevated HDL levels but also hindered tumor development and improved survival rate." (PMID 36557213, 2022). "Studies have shown that APOA1 exerts anti-tumor effects mainly by inhibiting tumor cell proliferation and promoting apoptosis." (PMID 35421932, 2022).